DPP3 (dipeptidyl peptidase 3)
Diseases named in the same sentence as DPP3 in open-access papers (continued):
Sharing a sentence is not in itself a finding about the gene and the disease.
cancer (15 papers, 2018 to 2025). A tumor composed of atypical neoplastic, often pleomorphic cells that invade other tissues. "Additionally, DPP3 has been implicated in the protection of cancer cells from oxidative damage by a mechanism that inhibits the NRF2 ubiquitination." (PMID 29304092, 2018). "In fact, the Keap1–Nrf2 antioxidant system, which comprises also Dpp3 among its activators, is known to exert both protective and detrimental effects, in cancer as well as in bone biology, acting both on the osteoclast and on the osteoblast lineage." (PMID 35745051, 2022). "This suggested a potential role of DPP3 in cancer development." (PMID 39941813, 2025). "DPP3 is upregulated in cancer and might serve as a key factor in the tumorigenesis and progression of various malignancies." (PMID 38655619, 2024). "Emerging studies have shown that DPP3 expression is upregulated in some types of cancers [5‒8]." (PMID 38655619, 2024). "However, little information is available on the expression, specificity, and function of DPP3 in human cancers." (PMID 34023852, 2021). "Previous studies indicated the involvement of DPP3 in cancer." (PMID 34023852, 2021). "In addition, previous reports have indicated that DPP3 is related to a variety of cancers." (PMID 34023852, 2021). "In addition, we explored whether DPP3 impacts the proliferation of cancer cells through autophagy." (PMID 38655619, 2024). "Correlation between mRNA expression of DPP3 and genes involved in the NRF2 pathway was assessed using publicly available gene expression datasets of multiple cancer types in the TCGA study." (PMID 37531267, 2023). "Recently, the dipeptidyl peptidase III (DPP3) was identified as a Keap1 interacting protein, which blocks Nrf2-Keap1 interactions and activates Nrf2-dependent transcription in cancer cells." (PMID 31022969, 2019). "DPP3 expression was assessed in normal and tumor tissues using quantitative real-time (qRT)-PCR and corroborated with ESCC gene expression datasets from Gene Expression Omnibus (GEO) and The cancer genome atlas (TCGA)." (PMID 37531267, 2023). "Further, Nrf2 ubiquitination and the binding affinity of Nrf2 to Keap1 is reduced in cancer cells by the competition of endogenous signaling molecules, such as p62, partner and localizer of BRCA2 (PALB2), and dipeptidyl-peptidase 3 (DPP3), with Nrf2 to bind to Keap1." (PMID 33050575, 2020). "In addition to its role in protein turnover, evidence suggests that DPP3 could be involved in more specific roles such as inhibition of the NF-E2–related factor 2 (NRF2) ubiquitination, which promotes the oxidative damage survival of cancer cells." (PMID 29304092, 2018).
tumor (12 papers, 2014 to 2024). "The autophagy marker LC3-II/LC3-I ratio increased inDPP3-KO MDA-MB-231 cells, suggesting that the loss of DPP3 might enhance autophagy in tumor cells." (PMID 38655619, 2024). "Immunohistochemistry results showed that the expression of DPP3 in individual tumor sample from the HPA database was positively correlated with FASN." (PMID 38655619, 2024). "This was further confirmed by the assessment of DPP3 mRNA expression in our institutional cohort containing tumor and adjacent normal tissues from 41 EC patients." (PMID 37531267, 2023). "Subsequently, the correlation between DPP3 expression and tumor characteristics was analyzed, revealing the role of DPP3 in the progression and prognosis of CRC patients." (PMID 34023852, 2021). "Spearman’s correlation analysis for the mRNA expression of NRF2 pathway genes in normal and tumor tissues from our institutional cohort also revealed high concordance in expression between DPP3 and NRF2 pathway genes, including NFE2L2, KEAP1, and NQO1 in tumors, but not in normal tissues." (PMID 37531267, 2023). "Among the proteins containing Keap1-interacting region (KIR)-like ETGE motifs, which compete with the Nrf2 in binding to Keap1, are p62/sequestosome 1 (SQSTM1), dipeptidyl peptidase 3 (DPP3), the Wilms tumor gene on the X chromosome (WTX) and a partner and localizer of BRCA2 (PALB2)." (PMID 34502501, 2021). "Furthermore, the small volume and light weight of solid tumors also suggested that tumor growth slowed down after DPP3 silencing." (PMID 34023852, 2021). "In addition, several other proteins, such as DPP3 (dipeptidyl-peptidase 3) or WTX (Wilms tumor gene on X chromosome), can interact with Keap1 and modulate the Nrf2-Keap1 pathway." (PMID 29438305, 2018). "Therefore, we speculated that DPP3 might promote tumor progression by regulating FASN." (PMID 38655619, 2024). "The other Keap1 binding proteins, such as the Wilms tumor gene on the X chromosome (WTX), PALB2/FANCN, and dipeptidyl peptidase 3 (DPP3) also contain the ETGE motif in common and can promote the Nrf2 protein stability by competitively binding to Keap1." (PMID 25014534, 2014). "Subsequent experiments show that DPP3 could stabilize FASN expression and thus promote fatty acid synthesis in tumor cells." (PMID 38655619, 2024). "Interestingly, clustering based on Spearman’s correlation value of NRF2 pathway genes revealed that DPP3 exhibited a strong correlation to several NRF2 target genes, which differed widely among tumor types." (PMID 37531267, 2023). "Similarly, we assessed the mRNA expression of DPP3 in ESCC patients, which also suggested higher expression of this peptidase in tumor tissues compared with normal esophageal epithelia." (PMID 37531267, 2023). "Unlike its family member DPP4, the role of DPP3 in tumor biology is much less clear." (PMID 38655619, 2024). "However, a comparison of DPP3 expression based on tumor stage and grade did not suggest any significant difference in DPP3 expression with increasing stage or grade of tumor in the TCGA dataset (respectively)." (PMID 37531267, 2023).
infection (2 papers, 2012 to 2025). The state of being infected such as from the introduction of a foreign agent such as serum, vaccine, antigenic substance or organism. "Interestingly, RNAi of DPP3 using siDPP3 significantly (p<0.05) increased CRE/CREB activation under mock-infected conditions despite DPP3 not being implicated in the CRE/CREB pathway, and silencing of ADAMTS7 significantly (p<0.05) abrogated CRE/CREB activation during infection." (PMID 22606348, 2012).
cardiovascular diseases (1 paper, 2022). "It will provide a theoretical basis for exploring the potential value of DPP3 as a therapeutic target for cardiovascular diseases." (PMID 36312232, 2022). "Especially in cardiovascular diseases, DPP3 is regarded as a marker of more severe disease with higher activity of renin-angiotensin system (RAS)." (PMID 36312232, 2022). "At present, the concentration and activity of DPP3 in circulation can accurately predict the severity of acute cardiogenic shock patients, which undoubtedly provides an important basis for the prevention and diagnosis of cardiovascular diseases." (PMID 36312232, 2022). "Therefore, it is still of great significance to clarify the efficacy of DPP3 as a biomarker and to explore its potential therapeutic value in patients with cardiovascular disease for the diagnosis and prevention of cardiovascular disease." (PMID 36312232, 2022). "Hence, this review summarizes the recent advances in the structure and catalytic activity of DPP3 and its extensive biological functions, especially its role as a therapeutic target in cardiovascular diseases." (PMID 36312232, 2022). "With the in-depth exploration of DPP3, a large amount of evidence shows that it is not only a biomarker of cardiovascular disease, but also participates in the occurrence and development of cardiovascular diseases through pathways such as RAS, oxidative stress, and inflammation." (PMID 36312232, 2022). "Therefore, this review will summarize the biological characteristics of DPP3 and its research progresses in cardiovascular diseases, which aims to provide a theoretical basis for exploring potential value of DPP3 as a therapeutic target for cardiovascular diseases." (PMID 36312232, 2022). "Besides the over-activation of RAS, oxidative stress may also be a critical mediator between DPP3 and cardiovascular diseases." (PMID 36312232, 2022). "However, there is still a lack of unified understanding of the role of DPP3 in diagnosing and treating cardiovascular diseases." (PMID 36312232, 2022).
DPP3 also shares sentences with these, for which no sentence is quoted: ovarian carcinoma (3 papers); type 2 diabetes (3); esophageal squamous cell carcinoma (2); respiratory infections (2); acute coronary syndrome (1); cardiac arrest (1); coagulopathy (1); diabetes (1); heart diseases (1); Hyperglycemia (1); liver cancer (1); lung carcinoma (1); lymphopenia (1); melanoma (1); pneumonia (1); renal dysfunctions (1); viral diseases (1).